RPL5 (ribosomal protein L5)
Diseases named in the same sentence as RPL5 in open-access papers (continued):
Sharing a sentence is not in itself a finding about the gene and the disease.
microcephaly (2 papers, 2022 to 2025). A congenital or acquired developmental disorder in which the circumference of the head is smaller than normal for the person's age and sex. "Upon Rpl5 knockdown using an antisense-based morpholino oligonucleotide approach, we showed different phenotypes affecting anterior tissue, i.e., defective cranial cartilage, malformed eyes, and microcephaly." (PMID 35281111, 2022). "Ribosomal proteins other than Rpl5 also affect proper eye as well as brain development as Pescadillo homologue 1 (Pes1) and Peter Pan (Ppan) lead to malformed eyes, including coloboma, as well as microcephaly in developing Xenopus laevis." (PMID 35281111, 2022). "We prioritized these four RP genes due to their involvement in human ribosomopathies, with rpl-5, rpl-33, and rps-10 relating to DBA, and rps-23 relating to microcephaly and intellectual disability without the blood phenotypes." (PMID 39786340, 2025).
multiple sclerosis (2 papers, 2010 to 2020). A progressive autoimmune disorder affecting the central nervous system resulting in demyelination. "Recent association studies in multiple sclerosis (MS) have identified and replicated several single nucleotide polymorphism (SNP) susceptibility loci including CLEC16A, IL2RA, IL7R, RPL5, CD58, CD40 and chromosome 12q13–14 in addition to the well established allele HLA-DR15." (PMID 20368992, 2010).
non-small cell lung carcinoma (2 papers, 2019 to 2022). A group of at least three distinct histological types of lung cancer, including non-small cell squamous cell carcinoma, adenocarcinoma, and large cell carcinoma. "JiEonPark and other scholars have found that SanG can inhibit the proliferation of non-small cell lung cancer cells and induce their apoptosis through the combination of caspase-3 activation and RPL5-mediated c-Myc inhibition and doxorubicin in their research on the effect of Sangenong (SanG)." (PMID 36384455, 2022).
bone marrow failure syndrome (1 paper, 2019). "Results of our study demonstrate that analysis of NGS gene panel assays for CNVs can not only establish a genetic diagnosis (such as identifying RPL5 mutations in patients with DBA), but can also identify the specific diagnosis in unclassified or idiopathic bone marrow failure syndromes." (PMID 31839986, 2019).
clear cell sarcoma of the kidney (1 paper, 2018). "On the other hand, when compared with Wilms’ tumor and clear cell sarcoma of the kidney, RPL5 and RPL10 were signifcantly downregulated in KRT." (PMID 30479569, 2018).
erythroblastopenia (1 paper, 2019). "Similarly, treated shRNA Rpl5+/- mice developed reticulocytopenia and bone marrow erythroblastopenia." (PMID 32309614, 2019).
heart failure (1 paper, 2020). Inability of the heart to pump blood at an adequate rate to meet tissue metabolic requirements. "RPL5 was also a stable gene when studying heart failure of the right ventricles in humans and tissues of red abalone Haliotis rufescens (Mollusca, Vetigastropoda)." (PMID 32841273, 2020).
Infertility (1 paper, 2024).
keratitis (1 paper, 2010). A corneal disease that is characterized by inflammation of the cornea. "Namely, geNorm proposed PPIA and HRPT1 and PPIA and RPL5 pairs for chemical burn-induced CorNV in Balb/c and C57BL/6 mice, respectively, while UBC and HPRT1 and UBC and LDHA were best for Candida and Aspergillus induced keratitis in Balb/c mice, respectively." (PMID 20596249, 2010).
leishmaniasis (1 paper, 2021). Infectious disease that is transmitted through the bite of hematophagous female phlebotomine sand flies. "We could not compare our results because there are no similar studies that use the ribosomal protein L5 gene as a DNA vaccine against Leishmaniasis caused by Leishmania tropica." (PMID 34094593, 2021).
lymph node metastasis (1 paper, 2022). "Moreover, we found RPL5 expression was closely linked to TNM stage, tumor size, and lymph node metastasis, but had little relationship with age." (PMID 35293275, 2022).
medulloblastoma (1 paper, 2018). A malignant, invasive embryonal neoplasm arising from the cerebellum. "Compared with medulloblastoma, RPL5 and RPL10 were signifcantly upregulated in AT/RT, with fold changes of 1.25 and 1.5 (p < 0.001), respectively." (PMID 30479569, 2018). "After comparison with other common pediatric tumors, RPL5 and RPL10 can also be used to distinguish AT/RT from medulloblastoma." (PMID 30479569, 2018).
neuroblastoma (1 paper, 2016). Neuroblastoma (NB) is the most common solid, extracranial childhood tumor.
osteosarcoma (1 paper, 2024). A usually aggressive malignant bone-forming mesenchymal neoplasm, predominantly affecting adolescents and young adults.
ovarian carcinoma (1 paper, 2024). A malignant neoplasm originating from the surface ovarian epithelium. "Furthermore, analysis of data from the Kaplan–Meier plot showed a correlation between higher expression of TCP1, RPL5, HSPA4, and CCT5 and poor prognosis in ovarian cancer." (PMID 39309198, 2024).
pediatric tumors (1 paper, 2018). "Together, these results suggest that RPL5 and RPL10 as promising diagnostic markers not only in distinguishing for AT/RT from normal tissues but also in from other types of pediatric tumors." (PMID 30479569, 2018).
rhabdoid tumor (1 paper, 2018). An aggressive malignant embryonal neoplasm usually occurring during childhood. "Our study mined existing GEO datasets for novel diagnostic markers associated with Rhabdoid tumors, and identified RPL5 and RPL10 as potential diagnostic markers for AT/RT." (PMID 30479569, 2018).
rhabdomyosarcoma (1 paper, 2023). A rare aggressive malignant mesenchymal neoplasm arising from skeletal muscle. "Relative to skeletal muscle fibroblasts, several rhabdomyosarcoma cell lines (RH18, RH28, RH36, RH41, RD, and Kym-1) showed higher levels of eL36/RPL36 and eL42/RPL36A, while uL18/RPL5 remained unchanged." (PMID 37047306, 2023).
tumor (62 papers, 2010 to 2026). "In some instances, it is the overexpression of mutated RPL5 proteins that promotes tumorigenesis and tumour progression." (PMID 40940922, 2025). "RPL5 downregulation is also associated with breast cancer cell proliferation and tumor progression in transgenic mice and human tumor xenograft mouse models." (PMID 34497807, 2021). "The observation of heterozygous inactivating RPL5 mutations and deletions across multiple tumor types suggested a role as haploinsufficient tumor suppressor gene." (PMID 28147343, 2017). "In our study, we found mutations in the RNA binding domains of RBM47 and RPL5, which are suggested to be tumor suppressors in a few cancers." (PMID 28035070, 2017). "It represents a candidate tumor suppressor, based on its heterozygous inactivating mutations and focal deletions and based on the correlation of lower RPL5 expression with worse survival." (PMID 28147343, 2017). "Collectively this suggests that loss of the tumor suppressive functions of RPL5 (uL18) or RPL11 (uL5) via inactivating mutations might predispose DBA patients to cancer development." (PMID 30862070, 2019). "Therefore, we aimed to experimentally test the effect of ~50% RPL5 loss-of-function on cell behavior in vitro and on tumor forming capacity in an in vivo mouse model." (PMID 28147343, 2017). "However, both studies showed impeded proliferation upon RPL5 loss, whereas we observed increased proliferation and tumor growth in our RPL5 haploinsuffiency cancer model." (PMID 28147343, 2017). "In cancerous cells, the ubiquitination of specific RPs can promote tumour invasion, tumour metastasis, and resistance to chemotherapy treatment, thereby contributing to tumour progression (see sections on RPL5, RPL11, RPS3, and RPL23a)." (PMID 40940922, 2025). "RPL5 and RPL10 are located in sites where decoding takes place inside the ribosome, and exhibit mutations with considerable frequency in tumor cells." (PMID 37958852, 2023). "As RPL5 performed both tumor activator and tumor suppressor in types of cancer cells, it’s possible that RPL11 has similar function in cancer cell growth." (PMID 36869281, 2023). "Overexpression of RPL5 inhibited tumor cell growth and knockdown of E2F1 transcriptionally activated GRP78." (PMID 35293275, 2022). "It is interesting to note that the Rabadan group integrated TCGA data with known causative genes in cancer predisposing Mendelian diseases, such as DBA, and that they also pick up RPL5 as candidate tumor suppressor in GBM in their analyses." (PMID 28147343, 2017). "Additionally, RPL5 promotes the increased expression of c-Myc, ultimately contributing to tumour proliferation and migration." (PMID 40940922, 2025). "Together these data are consistent with a role for wt rpL5 in tumor suppression." (PMID 39001453, 2024).
tumor (continued). "Loss of tumor suppressor “RPL5/RPL11” does not trigger cell cycle arrest but hampers proliferation by reducing ribosome content and translation capacity." (PMID 39001453, 2024). "Considering the small number of normal samples in TCGA, and to extend this comparison, we combined normal tissue data from the GTEx database and TCGA tumor tissue data to analyze the expression of 33 tumors and obtained consistent results: RPL5 expression was elevated in most tumors, including COAD." (PMID 36384455, 2022). "We found that RPL5 inhibited tumor cell growth and autophagy." (PMID 35293275, 2022). "For example, one study found decreasing the tumor suppressors RPL5 or RPL11 resulted in a reduction in ribosome content and translation capacity, causing cells to progress at a lower rate through all stages of the cell cycle thus resulting in decreased proliferation without cell cycle arrest." (PMID 29466962, 2018). "RPL5 may inhibit tumorigenesis through the activation of downstream tumor suppressors and the down-regulation of oncoprotein expression." (PMID 30479569, 2018). "Growth factor release by a supportive tumor microenvironment or other mechanisms such as tumor hypoxia, which cannot be mimicked in vitro, may explain why the RPL5 knockdown in MDA-MB-231 cells showed only a significant effect in the in vivo context." (PMID 28147343, 2017). "Similarly, more studies are needed to unravel the molecular mechanisms by which RPL5 exerts its tumor suppressor role in cancer." (PMID 28147343, 2017). "In this context, LUAD, KIRC, STAD and PRAD also show inactivating mutations or deletions in RPL5, suggesting that RPL5 may also act as a tumor suppressor in these tumor types." (PMID 28147343, 2017). "However, a closer analysis showed that the known cancer genes are more than 7 Mbp away from RPL5 and also in this tumor type RPL5 was located in a pronounced deletion peak." (PMID 28147343, 2017). "Similarly, the results of IHC analysis also showed that RPL5 was downregulated in tumor tissues." (PMID 35293275, 2022). "RPL5 and RPL11 collaborate to suppress c-Myc expression via miRNA-mediated mRNA degradation, thus acting as tumor suppressors." (PMID 40864769, 2025). "Through the analysis of normal tissue data in the TCGA database and tumor tissue data in the GTEx database and TCGGA database, it was found that RPL5 was highly expressed in COAD." (PMID 36384455, 2022). "RPS6, RPS19 and RPS25 helps in the transcription initiation of viral genes while RPL5 and RPL11 acts as tumor suppressors by degrading the mRNA of c-myc, through RNA induced silencing complex (RISC)." (PMID 29568375, 2018).
tumor (continued). "Conversely, the enrichment of RPL5 and RPS11 in T/NK cells indicates that lactylation may influence lymphocyte function and thus modulate the anti-tumor immune response." (PMID 40740857, 2025). "The upregulation of RPL5 or RPL11 is regulated through the depletion of MID1IP1, and the depletion of RPL5 and RPL11 activates c-Myc in MID1IP1-depleted HepG2 and Huh7 cells, suggesting that RPL5 and RPL11 are responsible for the regulation of c-Myc as tumor suppressors." (PMID 40864769, 2025). "RPL5 is necessary for the transport of 5S rRNA non-ribosome-associated cytoplasmic 5S rRNA to the nucleolus for assembly into ribosomes, and it may also function to inhibit tumorigenesis through the activation of downstream tumor suppressors and the down-regulation of the oncoprotein expression." (PMID 38069262, 2023). "Moreover, alterations of RPL5, RPL10, RPS15, RPL11, and RPL22 ribosomal proteins have been described in 10 to 40% of tumor types." (PMID 33462193, 2021). "To evaluate whether RPL5 and RPL10 can be used to distinguish AT/RT and KRT from other tumors, we compared the expression levels of RPL5 and RPL10 in RTs and other types of tumor." (PMID 30479569, 2018). "It is worth pointing out that RPL5 defects in other tumor types did not pass the threshold for retention in our pipeline." (PMID 28147343, 2017). "However, c-MYC upregulation does not fully explain the proliferation and tumor growth advantage conferred by RPL5 knockdown since it also occurs in MCF7 tumors despite c-MYC downregulation." (PMID 28147343, 2017). "Besides these well-established functions, human RPL5 and SYT (the AN3 homolog) have additional non-canonical roles in tumor suppression." (PMID 37961382, 2023). "Importantly, some RP genes (e.g., RPL5, RPL11 and RPS20) are known to be tumor-suppressor genes, which is not the case for GATA1." (PMID 35328001, 2022).